KRTAP1-1 (keratin associated protein 1-1)
Description:
In the hair cortex, hair keratin intermediate filaments are embedded in an interfilamentous matrix, consisting of hair keratin-associated proteins (KRTAP), which are essential for the formation of a rigid and resistant hair shaft through their extensive disulfide bond cross-linking with abundant cysteine residues of hair keratins. The matrix proteins include the high-sulfur and high-glycine-tyrosine keratins.
Synonyms: KAP1.1; KAP1.6; KAP1.7; KRTAP1.1; KAP1.1B; HB2A; KAP1.1A; KRTAP1A; hKAP1.7
Tractability: No criterion of Open Targets' tractability assessment is met for any kind of drug.
Gene: Protein-coding gene on chromosome 17 (41,040,541 to 41,041,450, reverse strand). Ensembl gene ENSG00000188581.
Pathways (Reactome):
Developmental Biology: Keratinization
Gene Ontology:
Molecular function: protein binding
Cellular component: cytosol; keratin filament
Genetic constraint (gnomAD): Loss-of-function variants: 9 observed, 14.06 expected, observed/expected ratio (o/e) 0.64, 90% interval 0.38 to 1.12. The upper end of that interval is the gene's LOEUF score, 1.12, which puts it in group 4 of 6, group 1 being the genes least tolerant of losing a copy. Missense variants: 179 observed, 227.73 expected, observed/expected ratio (o/e) 0.79, 90% interval 0.69 to 0.89. Synonymous variants: 77 observed, 77.18 expected, observed/expected ratio (o/e) 1, 90% interval 0.83 to 1.21.
Homologues: Orthologues: chimpanzee KRTAP1-1 (97% identical), mouse Krtap1-5 (46% identical), rat Krtap1-5 (45% identical). Paralogues in human: KRTAP1-3 (89% identical), KRTAP1-5 (84% identical), KRTAP1-4 (62% identical), KRTAP4-12 (40% identical), KRTAP4-6 (39% identical), KRTAP4-11 (38% identical), KRTAP4-3 (37% identical), KRTAP4-9 (36% identical), KRTAP4-5 (35% identical), KRTAP4-4 (34% identical), KRTAP9-1 (34% identical), KRTAP9-2 (34% identical), and 35 more.
Diseases named in the same sentence as KRTAP1-1 in open-access papers:
KRTAP1-1 is named in the same sentence as 4 diseases in open-access papers, as found by Europe PMC text mining. Sharing a sentence is not in itself a finding about the gene and the disease. The quoted sentences say what the papers report.
metastatic disease (2 papers, 2015 to 2023). "Consistent with our immunoblotting observations under ex vivo and in vivo conditions, MEGF10, KRTAP1-1, SEMA3D, MYC, and GRB10 IHC staining revealed relatively strong positivity in metastatic tumors." (PMID 26148557, 2015). "Consistent with our immunoblotting data, we observed a profound and significant (P < 0.001) increase in the expression of KRTAP1-1 in the metastatic tumors as opposed to the non-metastatic controls." (PMID 26148557, 2015).
depression (1 paper, 2021). "Thus, we observed a significant association between remission to SSRI treatment and a LOF variant, rs3213755, in the KRTAP1-1 gene in elderly Korean patients with depression." (PMID 33633223, 2021).
KRTAP1-1 also shares sentences with these, for which no sentence is quoted: neuroblastoma (1 paper); tumor (1).